HDAC4 (histone deacetylase 4)
Diseases named in the same sentence as HDAC4 in open-access papers (continued):
Sharing a sentence is not in itself a finding about the gene and the disease.
tumor (continued). "HDAC4, which belongs to class IIa of the HDAC family, may contribute to tumor development and progression through multiple mechanisms." (PMID 34986849, 2022). "Likewise, when Spaety and co-workers treated nude mice harboring intradermal tumors derived from HSC39 human GC cells with cisplatin and the HDAC4 inhibitor, LMK235, tumor growth was strongly decreased." (PMID 36358890, 2022). "Further supporting a tumor-suppressor role for miR-22, oncogenes such as galectin-1 (LGALS1), ezrin (EZR), histone deacetylase 4 (HDAC4) tyrosine 3-monooxygenase/tryptophan 5-monooxygenase (YWHAZ), specificity protein 1 (SP1), and basigin (CD147) were reported to be hepatic targets of miR-22." (PMID 36139435, 2022). "As a result, tumor volume and weight were found to be reduced in the presence of HDAC4 or IRAK1 knockdown either under or not under irradiation, while the reduction was more substantial in the presence of irradiation (8 Gy)." (PMID 35193602, 2022). "Although there is no direct report on the relationship between HDAC4 and tumor immunity, studies believe that HDAC4 can affect IFN signal." (PMID 34880761, 2021). "Tasquinimod is a high-affinity HDAC4-selective negative allosteric modulator for HDAC4 that can suppress tumor angiogenesis." (PMID 33542203, 2021). "Moreover, the protein level of KEAP1 in the nude mice xenograft model was significantly upregulated in the tumor of circKEAP1 overexpression group, which in turn downregulated the protein level of NRF2 and HDAC4." (PMID 34136401, 2021). "Functionally, HDAC4 accelerated cell cycle G1/S transition and induced the epithelial-to-mesenchymal transition to promote NPC cell proliferation, migration, and invasion in vitro, as well as tumor growth and lung metastasis in vivo." (PMID 33542203, 2021). "Apicidin downregulates HDAC3 and HDAC4 and suppresses the tumor growth of transplanted Ishikawa cells, the expression of proliferative cell nuclear antigen (PCNA), and vascular endothelial growth factor (VEGF) in tumor xenograft model, respectively." (PMID 34804263, 2021). "Here, HDAC4 and HDAC5 were shown to mediate the regulation of AMPK on tumour metabolism." (PMID 32519437, 2020). "The results suggest that HDAC4 and HDAC5 might play a mediating role in AMPK regulation of tumour cell metabolism." (PMID 32519437, 2020). "In MM cells, ectopic miR-29b was shown to downregulate major tumor promoting or anti-apoptotic mRNA targets, including CDK6, MCL-1, SP1, as well as mRNAs coding for epigenetic regulators, such as HDAC4 and DNMT3A/B, thus triggering cell cycle arrest and apotosis." (PMID 29290968, 2017). "Negative methylation/expression correlations were also found for HDAC4 (a chromatin modifier), ERBB3 (a known oncogene), as well as MARCKS and CXCR4; genes known to induce tumor cell invasion and therapeutic resistance in other tumor types." (PMID 26963385, 2016). "HDAC4 is a confirmed target of miR-29b in mouse osteoblast differentiation, but it has not been validated in tumor cells." (PMID 26441331, 2015). "Altogether, metabolomic data suggest that a decreased GPChol/PChol ratio isassociated with high-grade tumors and that the expression of HDAC1,HDAC4 and SIRT1 may influence tumor aggressiveness throughchanges in metabolomic profiles of tumors." (PMID 25791281, 2015). "Targets of miR-155, such as histone deacetylase 4 (HDAC4), suppressor of cytokine signaling-1 (SOCS1) and immune cells, play a crucial role in DLBCL pathogenesis, since miR-155 regulates key pathways, transcription factors and cytokine expression and shapes the tumor microenvironment in DLBCL." (PMID 39767565, 2024). "In a “synthetic lethality” scenario, the combination of blocking HDAC4 and using monoclonal antibodies against VEGF, such as bevacizumab, may be promising in the overwhelming landscape of tumor resistance, and some encouraging results have already been obtained." (PMID 36762207, 2023).
tumor (continued). "Chicken chorioallantoic membrane (CAM) studies confirmed the in vitro results: Cal27_HDAC4 tumors were slightly larger than tumors from Cal27_VC, and treatment with CHDI0039 resulted in a significant decrease in tumor size and weight of Cal27_HDAC4 but not Cal27_VC." (PMID 36982651, 2023). "Notably, the expression of ALKBH5 or HIF1α was increased in PC tissues, while the expression of HDAC4 was not significantly different between normal and tumor tissues." (PMID 37149664, 2023). "However, there is quite a consensus in the literature that HDAC4, HDAC7, HDAC9, SIRT2, and SIRT7 are upregulated in GC and seem to be pro-tumor factors, whereas SIRT4, SIRT5, and SIRT6, which are downregulated, seem to have a tumor suppressor function." (PMID 36358890, 2022). "Similarly, knockdown of HDAC4 enhanced radiation-induced cell death, that of HDAC6 reduced the migration and invasion activities of all HCC cell lines, and that of HDAC8 repressed tumor cell growth and induced apoptosis." (PMID 30140374, 2018). "Furthermore, tumor aggressiveness and survival may besignificantly affected by the expression of just one gene (HDAC11 in GLand HDAC4 and HDAC6 in ODIII)." (PMID 25791281, 2015). "Thus, despite plasma levels of < 1 μM, the EPR effect results in intracellular drug concentrations of 2-3 μM, levels several-fold higher than needed for inhibition of endothelial sprouting (IC50 ~ 0.5 μM) or for inhibition of HDAC4 and S100A9 mediated tumor growth." (PMID 25193858, 2014). "Since a decreased GPChol/PChol ratio seems to beassociated with an increased malignancy and that the expression of some HDACswas correlated with survival, we stratified patients based on the expression ofHDAC1, HDAC4 and SIRT1 regardless of tumor grade andcompared their metabolomic profiles." (PMID 25791281, 2015). "From the past studies, HDAC2 itself had a positive effect on M2 polarization, whereas HDAC4 and HDAC11 had the negative effects on M2 polarization, suggesting that increasing HDAC4 and HDAC11 expression and decreasing HDAC2 expression are targets for tumor immunotherapy." (PMID 40375990, 2025).
infection (13 papers, 2010 to 2025). The state of being infected such as from the introduction of a foreign agent such as serum, vaccine, antigenic substance or organism. "More importantly, we found that infection of HDAC4 adenovirus in cardiomyocytes enhanced susceptibility to hypoxia/reoxygenation while knockdown of HDAC4 increased the resistance of myocytes to hypoxia/reoxygenation-induced injury." (PMID 27875543, 2016). "The amount of HDAC4-associated viral DNA steadily increased from 4 hours, with a peak reached at 8 hours post-infection." (PMID 20846395, 2010). "Moreover, infection with the influenza A virus has been reported to cause airway remodeling in asthmatic individuals via the indirect dysregulation of HDAC4." (PMID 32641122, 2020). "Viral DNA was found to be associated with HDAC4 at 4, 6, 8, and 16 hrs post-infection." (PMID 20846395, 2010). "However, we note that the inhibitor effect can be seen only at 8 hours post-infection, when the association of DNA with HDAC4 is at its peak." (PMID 20846395, 2010). "A similar anti-viral immune response role to foot-and-mouth disease virus (FMDV; coxsackievirus A16) was assigned to HDAC4 in a number of mammalian species as part of an interferon-mediated response in these host species to infection by FMDV." (PMID 39202383, 2024). "In this study, we identify ARID1A, PLEC and HDAC4 as predicted amiR-4 targets and show reduced gene expression and protein levels following VSVΔ51-amiR-4 infection." (PMID 35393414, 2022). "Here we show that VACV also induces the proteasomal degradation of HDAC4 during infection of several cell types and this requires protein C6, a virulence factor and multifunctional IFN antagonist." (PMID 31127039, 2019). "Further, addition of the proteasome inhibitor MG132 shortly after infection stabilized HDAC4 levels, demonstrating HDAC4 is targeted for proteasomal degradation." (PMID 31127039, 2019). "Real-time PCR analysis showed that HDAC4 siRNA infection resulted in 36.3% knockdown of HDAC4 mRNA levels (***P<0.001)." (PMID 24896240, 2014). "If the effect of nuclear HDAC4 on infection efficiency is due its role in PIR, it should prevent PIR-associated cell death." (PMID 20846395, 2010). "To determine if infection with HIV-1-based vectors induces the formation of HDAC4 foci, we have infected HeLa cells at a high multiplicity of infection, fixed infected cells at predetermined time points and stained with the HDAC4 antibody." (PMID 20846395, 2010). "We show that infection with retroviral vectors induces, similar to DSBs, nuclear foci of the HDAC4 protein." (PMID 20846395, 2010). "The supernatants of D-lactate-producing Lactobacillus spp.(L. crispatus and L. jensenii) modulate the expression of multiple genes related to cell proliferation including decreasing miR-193b and histone deacetylase 4 (HDAC4) which are required for CT-induced proliferation during infection." (PMID 36909729, 2023). "We found that the gene products encoded by ARID1A, PLEC and HDAC4 but not MCM2 were specifically decreased following infection with VSV∆51-amiR-4 as shown by RT-qPCR and immunoblotting analysis." (PMID 35393414, 2022). "This showed that HDAC4 was down-regulated during infection, while HDAC1 remained stable." (PMID 31127039, 2019). "Furthermore, HDAC4 was targeted for proteasomal degradation early after infection with VACV, and VACV protein C6, an inhibitor of type I IFN signaling, was necessary and sufficient for this degradation." (PMID 31127039, 2019). "After infection, CD147, HDAC4 and MMP-9 mRNA levels reduced over time in association with increased miR-22 expression which prevents CD147 protein induction by maintaing its levels unchanged, and reduces HDAC4 and MMP-9 protein levels after infection in pBECs from non-asthmatics." (PMID 30068332, 2018). "However, we also observed the appearance of HDAC4 foci in infected cells, with the majority of cells containing foci at 8 hrs post-infection." (PMID 20846395, 2010).
infection (continued). "Similarly, we have observed that HDAC4 is predominantly cytoplasmic at 4 and 6 hours post-infection." (PMID 20846395, 2010). "Moreover, infection with HIV-1-based vectors induces foci of the HDAC4 protein." (PMID 20846395, 2010). "In contrast, in pBECs from asthmatics, the expression of CD147 increased but miR-22, HDAC4 and MMP-9 expression remained unchanged after infection." (PMID 30068332, 2018). "Unlike WT VACV, infection with a VACV lacking the C6L gene was unable to induce degradation of HDAC4." (PMID 31127039, 2019). "After 24 h of infection, miR-22 expression increased significantly which was associated with the suppression of CD147 mRNA and HDAC4 mRNA and protein expression in pBECs from non-asthmatics, cultured in ALI." (PMID 30068332, 2018). "These led to lower levels (P = 0.004) of HDAC4 in non-asthmatics compared with asthmatics at 24 h post infection." (PMID 30068332, 2018). "Also, administration of specific inhibitors of c-Myc or SP-1 during infection in cells from both groups, will determine the regulatory roles of these transcription factors on CD147 and HDAC4 in epithelial cells." (PMID 30068332, 2018). "Also, MMP-9 expression and activity are congruent with CD147 and HDAC4 expression in pBECs after infection particularly in cells from non-asthmatics." (PMID 30068332, 2018). "However, HDAC4 protein expression was not affected by infection in cells from asthmatics." (PMID 30068332, 2018).
neurodegenerative disease (12 papers, 2014 to 2024). A disorder of the central nervous system characterized by gradual and progressive loss of neural tissue and neurologic function. "Understanding the roles of nuclear and cytoplasmic HDAC4 and mechanisms regulating its nuclear entry and exit is an area of concerted effort due to the association of nuclear accumulation of HDAC4 with neurodevelopmental and neurodegenerative disease." (PMID 38167120, 2024). "HDAC4 has a significant role in this neurodegenerative disease, affecting the kinetics of body weight, muscle function, and atrophy, in both male and female mice." (PMID 36613534, 2022). "Therefore, what appears to be noxious in many neurodegenerative diseases, namely the nuclear localization of HDAC4, is seemingly beneficial in the context of chronic inflammatory pain for preventing the development of hypersensitivity." (PMID 35169129, 2022). "Because there are no selective HDAC4 inhibitors, we decided to work with NaBut, an HDAC pan-inhibitor that easily penetrates the blood–brain barrier and that has shown potential in several neurodegenerative diseases and models, administered systemically." (PMID 37756598, 2023).
cardiovascular diseases (7 papers, 2016 to 2024). "Seven of these DMPs (25%) could be allocated to a gene that was previously associated with cardiovascular diseases (HDAC4, IGF2BP3, CASZ1, SDK1, PCDHGA1, DIO3, PTPRN2)." (PMID 34895303, 2021). "Together, our studies identify AQP1 as a novel epigenetic regulator of HDAC4-Mef2A-dependent EC senescence and angiogenic potential, highlighting its potential as a therapeutic target for antagonizing age-related cardiovascular diseases." (PMID 39180980, 2024). "HDAC4 is one of these genes that has been connected to cardiovascular disorders, where in cultured cardiomyocytes, it regulates neointimal hyperplasia by inducing the proliferation and migration of vascular smooth muscle cells." (PMID 35629146, 2022). "Most interestingly in relation to aortic diameters, seven genes were found to have a known role in the cardiovascular system, of which HDAC4 is the most widely studied in cardiovascular disease." (PMID 34895303, 2021). "It is possible that JMJD2A participates in such adaptive responses together with other proteins present in cardiovascular diseases including HDAC4 or HP1." (PMID 27722168, 2016).
neurological diseases (6 papers, 2019 to 2025). "Rtn1, a gene involved in membrane trafficking and regarded as a marker for neurological diseases, was downregulated in rotenone-exposed N27 cells, possibly mediated by HDAC4 downregulation." (PMID 39188570, 2024). "For example, PI3K/Akt pathway is involved in regulating the function of histone deacetylase 4 (HDAC4), while HDAC4 plays a pivotal role in various neurological diseases including AD." (PMID 31036051, 2019).
neurodevelopmental disorder (3 papers, 2022 to 2025). A behavioral and cognitive disorder with onset during the developmental period that involves impaired or aberrant development of intellectual, motor, or social functions. "Aberrant nuclear accumulation of HDAC4 has been associated with several neurodegenerative and neurodevelopmental disorders." (PMID 41151763, 2025). "Mutations in HDAC4 gene are causative of Neurodevelopmental disorder with central hypotonia and dysmorphic facies (OMIM #619797)." (PMID 38753158, 2024). "To date, three neurodevelopmental disorders caused by mutations in genes encoding for HDACs (HDAC4, HDAC6 and HDAC8) and thus belonging to the group of chromatinopathies, have been described." (PMID 38753158, 2024). "However, it took a long time for HDAC4 to be enrolled in the OMIM database, and it has been recently linked to ‘neurodevelopmental disorder with central hypotonia and dysmorphic facies' (#619797) in OMIM during March 2022." (PMID 35937050, 2022).
kidney diseases (2 papers, 2015 to 2022). "Therefore, HDAC4 is a critical epigenetic mediator in the pathogenesis of DN, and specific inhibition of HDAC4 could serve as a therapeutic approach for DN and related renal diseases." (PMID 25972812, 2015).
metabolic disease (2 papers, 2017 to 2020). A congenital disorder (due to inherited enzyme abnormality) or acquired (due to failure of a metabolically important organ) disorder resulting from an abnormal metabolic process. "Another enzyme being specifically correlated to metabolic disease and gluconeogenic gene expression, the mitochondrial protein pyruvate dehydrogenase kinase 4 (Pdk4), was strongly inhibited in livers of mice treated with HDAC4/5/7 siRNAs." (PMID 32982982, 2020). "Histone deacetylase 4 (HDAC4) and histone deacetylase 5 (HDAC5) are chromatin remodeling enzymes and critical regulators of muscle oxidative and metabolic function; these genes are coordinately down-regulated in metabolic diseases such as obesity." (PMID 28045116, 2017).
immune disorder (1 paper, 2022). "Meanwhile, because HDAC4 can regulate the development and functions of immune cells, it might reflect the degree of immune disorder to some extent." (PMID 35602496, 2022).
inflammation (1 paper, 2022). Aberrant reaction of the microcirculation characterized by movement of fluid and leukocytes from the blood into extravascular tissues. "Increased expression of HDAC4 is associated with vascular inflammation and associated inflammatory diseases via the activation of autophagy, and knockdown of HDAC4 ameliorates vascular inflammation." (PMID 35645372, 2022).
muscular disorder (1 paper, 2010). "Especially, HDAC4 and CNFR seem to be nice candidates to muscular disorder." (PMID 20074336, 2010).
skeletal dysplasia (1 paper, 2025). Any Mendelian diseases that affects growth and development of the skeleton. "Overall, targeting the miR-140/Hdac4/BMP axis could therefore present unique opportunities to treat skeletal dysplasias and prevent premature hypertrophy." (PMID 40225327, 2025).
HDAC4 also shares sentences with these, for which no sentence is quoted: chondrosarcoma (5 papers); hypertrophy (5); liposarcoma (3); lymphoma (3); skeletal muscle atrophy (3); adenocarcinoma (2); behavioral disorders (2); bipolar disorder (2); brain diseases (2); Cirrhosis (2); CNS tumors (2); cocaine addiction (2); dyslipidemia (2); fibrosis (2); lung adenocarcinoma (2); nevus (2); Parkinson (2); Seizure (2); virus infection (2); ablepharon macrostomia syndrome (1); acromelic dysplasia (1); angina (1); Barber-Say syndrome (1); benign prostate hyperplasia (1); bone disorder (1); calcification (1); chronic kidney disease (1); Coffin-Siris syndrome (1); colorectal adenocarcinoma (1); Cornelia de Lange syndrome (1).
A further 49 diseases each share a sentence with HDAC4 in 1 paper.